CXCL12 (C-X-C motif chemokine ligand 12)
Diseases named in the same sentence as CXCL12 in open-access papers (continued):
Sharing a sentence is not in itself a finding about the gene and the disease.
tumor (continued). "Biologics, such as mAbs and ligand traps, selectively target the receptor (CXCR4) or ligand (CXCL12) to inhibit a signalling loop that promotes tumour survival, immune suppression, and chemoresistance." (PMID 41002447, 2025). "Elevated levels of CXCR4 in tumor cells are frequently accompanied by high expression of its ligand CXCL12 within tumor-harboring lymph nodes." (PMID 41149503, 2025). "Loss of lymphatic-specific CXCL12 or CXCR4 inhibition boosts T cell retention and enhances tumor control." (PMID 41511312, 2025). "It has been revealed that elevated expression of CXCL12 is significantly correlated with high tumor stage, the presence of lymph node and distant metastases." (PMID 40943634, 2025). "CXCL12 stimulates tumor cell proliferation, movement, and invasion by activating of the AKT and ERK pathways." (PMID 40918470, 2025). "Advanced assays quantify circulating cytokines and chemokines, such as IL-6, TNF-α, and CXCL12, which reflect the immune microenvironment and tumor progression." (PMID 40881677, 2025). "CXCR4 is prominently expressed in both primary and metastatic ESCA lesions, enabling tumor cell homing to CXCL12-rich niches such as lymph nodes." (PMID 40134607, 2025). "SCs are able to secret multiple pro-tumor factors, such as IL-6, CXCL12, PGE2, etc. to participate in tumor progression." (PMID 40248695, 2025). "High levels of CXCL12 lead to the exhaustion of cytotoxic lymphocytes, impairing effective anti-tumor immune responses." (PMID 40739089, 2025). "The number of NK cells in CRC is limited, even if the levels of intratumoral IFN-γ, CCL3, CXCL10 and CXCL12 contributing to the NK cells recruitment to the inflamed tumor area are elevated." (PMID 40136652, 2025). "Activation of the sympathetic nervous system can elevate stromal SDF-1/CXCL12 and other chemotactic signals that draw tumor cells to the hematopoietic stem cell niche and bone." (PMID 41465319, 2025). "Future research should focus on discovering novel cytokine and growth factor biomarkers, particularly underexplored molecules like IL-10, TGF-β, and CXCL12, which influence immune evasion and tumor progression." (PMID 40881677, 2025). "High-definition Stereo-seq volumes show that these vessels articulate long, finger-like processes that penetrate deep into the viable tumour mass, guiding CXCL12-secreting cancer-associated fibroblasts and SOX9 + stem-like tumour cells into close proximity." (PMID 40740859, 2025). "The inclusion of CXCR4E was intended to block the suppressive pathway driven by cancer-associated fibroblast secretion of CXCL12, which binds CXCR4 on T cells to hinder their tumor engagement and dampen responsiveness to CXCL10." (PMID 41294574, 2025). "Currently, the CXCL12/CXCR4 axis is thought to involve several tumor‐related signaling pathways in the HCC process, such as nuclear factor (NF)‐κ B, PI3K/protein kinase B (AKT), and c‐Jun amino‐terminal kinase (JNK)." (PMID 40145607, 2025). "We previously reported that QRHXF plays a significant role in suppressing tumor formation in vivo, primarily through the modulation of inflammation and the CXCL12/CXCR4/JAK2/STAT3 signaling pathway by regulating TAMs." (PMID 40670983, 2025). "Over the past decade, several CAFs-derived chemokines such as interleukin-6 (IL-6), C-X-C motif chemokine ligand 12 (CXCL12), and C-C motif chemokine ligand 2 (CCL2) have been implicated in the mechanisms driving tumor progression." (PMID 41408647, 2025). "Interactions between CXCR4 and its ligand, CXCL12, support tumor growth by enhancing angiogenesis, immune evasion and resistance to therapies, as well as tumor metastasis." (PMID 40227824, 2025). "Updating evidences suggest a more complicated function of tumor‐derived chemokines, such as CCL22 and CXCL12 in orchestrating tumor immune evasion." (PMID 41427020, 2025). "By recruiting immunosuppressive cells such as Treg cells and M2 macrophages, the CXCL12/CXCR4 signaling pathway plays a critical role in tumor immune escape." (PMID 41376630, 2025).
tumor (continued). "Protein-array profiling indicated that CXCL12 silencing broadly reduced pro-tumor mediators in CAF-conditioned medium (e.g., IL-6, TGF-β1, VEGF, FGF, EGF, and MCP-1) while increasing anti-angiogenic factors such as serpin B5 and thrombospondin-2." (PMID 41514658, 2025). "The extensive expression of CXCR4 in cancer, coupled with the constant presence of CXCL12 in various organs, drives the activation of this axis, which in turn facilitates angiogenesis, tumor progression, and metastasis." (PMID 40142155, 2025). "CXCL12 (SDF-1): CXCL12 can act as a chemoattractant to the tumor site for immune suppressor cells such as myeloid-derived suppressor cells (MDSCs) and Tregs, which in turn suppress TIL function." (PMID 40805183, 2025). "Initial Western blot results demonstrated a significant decrease in CXCR4 protein expression in the tumor tissues of mice treated with oe‐NC+M2pep‐Cs NPs/Plerixafor compared to the oe‐NC group; while, CXCL12 protein levels remained unchanged." (PMID 40536774, 2025). "In solid tumors, the stromal components and chemokines (e.g., CCL27, CXCL12) often prevent the infiltration of NK cells into the tumor core, limiting their ability to exert cytotoxic effects." (PMID 40076725, 2025). "In contrast, iCAFs secrete pro-inflammatory cytokines (e.g., IL-6, C-X-C motif chemokine ligand 12 (CXCL12)) to fuel tumor growth, while ApCAFs modulate adaptive immunity through antigen presentation, thereby shaping therapeutic responses in HCC." (PMID 41438763, 2025). "High levels of CXCR4 expression correlate with poor prognosis and increased metastasis, as it directs tumor cells toward sites rich in its ligand, CXCL12." (PMID 40242222, 2025). "This ultimately forms a self-amplifying loop where chemotherapy-induced hypoxia leads to unintentional CXCR4/CXCL12 activation and consequently tumour regrowth." (PMID 41002447, 2025). "Hypoxia triggers CXCL12 expression in many tumours by the HIF-1 dependent expression of CXCL12 synthesis." (PMID 40852716, 2025). "Studies on mouse models of PDAC have shown that the population of CAFs expressing SMA exhibit increased Shh signaling, which inhibit the production of VEGF, CXCL12, and IL-8, factors that promote angiogenesis, tumor growth, and immunosuppression in the TME." (PMID 40136652, 2025). "Plerixafor, a CXCL12 inhibitor, disrupted this axis and significantly enhanced anti‐tumor efficacy when combined with anti‐PD‐1 plus lenvatinib in vivo." (PMID 41028931, 2025). "During the invasion phase, EC promotes tumour invasion by modulating the microenvironment and activating Notch signalling via CXCL12 and transforming growth factor Beta (TGF‐β)." (PMID 40268524, 2025). "Tumor-associated macrophages (TAMs), comprising up to 50% of the tumor mass, are recruited via chemokine axes such as CCL2/CCR2, CX3CL1/CX3CR1, and CXCL12/CXCR4 and adopt an M2-like immunosuppressive phenotype, facilitating immune escape and angiogenesis." (PMID 41002423, 2025). "The CXCL12–CXCR4 axis drives the recruitment of CXCR4‐expressing tumor cells to CXCL12‐rich organs such as the lungs, facilitating metastatic seeding through chemotactic migration." (PMID 40470380, 2025). "The upregulated CXCL12/CXCR4 signaling pathway in GBM contributes to an immunosuppressive tumor immune microenvironment (TIME) and tumor progression, with AMD3100 as a CXCR4 inhibitor." (PMID 39866779, 2025). "The emergence of CAFs greatly influences the tumor microenvironment by releasing a plethora of cytokines, chemokines, growth factors, and exosomes such as VEGFA and CXCL12 to reciprocally complement the tumor growth." (PMID 40805183, 2025). "For example, matrix metalloproteinases secreted by CAFs degrade the ECM to facilitate tumor invasion, while factors like CXCL12 promote angiogenesis." (PMID 40755775, 2025). "Among these, CXCL12/CXCR4 signaling shapes a complex immunological landscape that supports tumor immune escape and progression." (PMID 40607416, 2025).
tumor (continued). "This pathway is critical in regulating cell growth and survival, indicating that the CXCL12/CXCR4 axis contributes to tumor aggressiveness." (PMID 40433410, 2025). "The enrichment of breast cancer CSCs through CXCL12/CXCR4 signalling is a contributor to prolonging tumour relapse and the propensity to metastasise post-treatment." (PMID 41002447, 2025). "The results showed that compared to the oe‐NC group, the CXCR4 and CXCL12 protein levels remained unchanged in the tumor tissues of the oe‐NC+M2pep‐Cs NPs/Plerixafor group." (PMID 40536774, 2025). "The mechanism of tumor proliferation is a multi-step process involving several factors and pathways, including the CXCL12/CXCR4 axis." (PMID 40142155, 2025). "In contrast, in breast cancer, they enhance tumor invasion by secreting CXCL12 and facilitating collagen contraction." (PMID 40656546, 2025). "For example, Zhongxing Liang and Tripti Khare identified that upregulation of VEGF and CXCR4 enhances tumor angiogenesis and promotes cancer cell colonization in distant organs, including the lungs, via the CXCL12/CXCR4 axis." (PMID 40777130, 2025). "A cascade of pro-tumorigenic factors, including IL6, VEGFA, IL11, PDGFA, and CXCL12, further amplify the formation of complex microenvironments that support tumor cell colonization and proliferation, exacerbating the progression of CRLM." (PMID 39979806, 2025). "In PCa, hypoxia induces CXCR4 expression via HIF-1α–dependent transcription, enhancing tumour cell chemotaxis toward CXCL12 (SDF-1) secreted by bone marrow stromal cells, a key mechanism promoting bone metastasis." (PMID 40806577, 2025). "Combination therapies represent an emerging and rational means by which to counteract the complex involvement of CXCR4/CXCL12 in tumour survival and metastasis, immune escape, and drug resistance." (PMID 41002447, 2025). "Secreting factors such as CXCL12 stimulate various signaling pathways such as AKTs responsible for promoting tumor development." (PMID 40377005, 2025). "Conversely, however, several studies have indicated that high levels of CXCL12 promote tumor growth, invasion, and poor prognosis in CRC." (PMID 40426863, 2025). "In contrast, ERα signaling is linked to increased tumor invasion via MMP9 production, activation of the CXCL12/CXCR4 pathway and the promotion of M2 macrophage polarization and infiltration." (PMID 40612952, 2025). "CXCL12 and S1P are chemotactic molecules that are upregulated in the tumor microenvironment of multiple malignancies." (PMID 40155684, 2025). "While clonally expanded CD8+ T cells and CXCL13 + B cells populate these micro-organs, their productive entry into tumour tissue is inhibited by a wall of CXCL12‐rich fibroblasts and by residual C1QC + macrophages with high STAT1/IL-1β signatures." (PMID 40740859, 2025). "CAFs can secrete various soluble cytokines and growth factors, including IL-6, TGF - β, and CXCL12, which bind to receptors on tumor cells and activate oncogenic signaling pathways such as JAK/STAT3, PI3K/AKT, and MAPK." (PMID 40959080, 2025). "The interaction between the TME and the tumor stimulates proliferation, survival, angiogenesis, and metastasis of the tumor itself, and all these pathways are in turn promoted by CXCL12." (PMID 40142155, 2025). "CXCR4/CXCL12 also facilitates the homing of tumour cells to distal organs while limiting therapeutic effectiveness due to protecting tumour cells from immune attack and apoptosis, making it an important therapeutic target." (PMID 41002447, 2025). "CD184 is highly expressed in SCLC cells, and its interaction with its ligand, CXCL12, promotes tumor growth and metastasis." (PMID 39941799, 2025). "In ductal carcinoma in situ (DCIS)-associated myoepithelial cells, genes regulating laminin and oxytocin receptor function are downregulated, while tumor-promoting genes like CXCL12 and CXCL14 are upregulated." (PMID 40647432, 2025).
tumor (continued). "CXCL12 levels >100 ng/mL have been demonstrated to promote tumor cell retention in the bone marrow microenvironment which contributes to drug resistance and immune clearance resistance." (PMID 41471085, 2025). "Tumor cells frequently overexpress CXCL12, which binds to CXCR4 on neutrophils, directing their recruitment and facilitating interactions with tumor cells." (PMID 39940643, 2025). "Tumor microenvironmental factors, including CAFs, contribute to CXCL12 production, with Twist-1 enhancing CXCL12 expression in these stromal cells." (PMID 40134607, 2025). "CXCL12 secreted by CAFs contributes to tumour proliferation, invasion, metastasis, immunosuppression, and angiogenesis." (PMID 39780187, 2025). "Chemokines such as CCL2, CCL5, and CXCL12 are known to recruit myeloid‐derived suppressor cells (MDSCs) to the tumor microenvironment, where they suppress T‐cell responses and promote tumor growth." (PMID 40145607, 2025). "One of the main players in this resistance is the CXCR4/CXCL12 signalling axis that is known to play a role in promoting tumour progression, metastasis, survival and remodelling the tumour microenvironment." (PMID 41002447, 2025). "A2BR signaling on CAFs also enhances CXCL12 secretion, which recruits Treg cells to the tumor and promotes T lymphocyte differentiation into CD25highFoxp3high subsets, potentially fostering pro-tumor effects both autocrine and paracrine." (PMID 40390144, 2025). "By examining how CXCL12 gradients direct neutrophil and tumor cell migration in vivo, deeper insights can be gained into the spatial dynamics of metastasis." (PMID 39940643, 2025). "•Cytokines like TGF-β and IL-10, along with chemokines such as CXCL12, establish an immunosuppressive microenvironment that promotes metastasis and tumor progression." (PMID 40242222, 2025). "The first cluster exhibits upregulation of CXCL12, PTGDS, KCNN3, suggesting CXCL12-high fibroblasts in the immune infiltrated stroma within the tumor microenvironment (TME)." (PMID 41249066, 2025). "Recently, tenascin-C was reported as a critical matrix molecule that impairs CD8+ tumor-infiltrating lymphocyte motility in a CXCL12-dependent manner." (PMID 40977682, 2025). "In conclusion, exosome-mediated HIF2A derived from primary tumor activates peritumoral fibroblasts to secrete CXCL12, thus preparing 'soil' enriched with CXCR4+ M2 macrophages for future invasion of cancer cell." (PMID 40756343, 2025). "CXCL12 produced by CAFs can mislead CTLs into the extracellular matrix of the tumor and prevent them from entering the tumor." (PMID 40046061, 2025). "Several inflammatory mediators, including interleukins (IL-6, IL-8, IL-10), tumor necrosis factor (TNF), and chemokines (CXCL12, CXCR4), are implicated in tumor progression and the pathological inflammatory microenvironment of these tumors." (PMID 40433410, 2025). "CAR‐NK cells engineered to additionally express CXCR4 have been shown to enhance direct migration towards CXCL12 in tumour‐infiltrated bone marrow compartments in mice in a haematological setting." (PMID 40159644, 2025). "Among them, gemcitabine (p = 0.001820) inhibits tumor cell migration by targeting the CXCL12/CXCR4 axis, potentially suppressing monocyte infiltration into atherosclerotic plaques through a similar mechanism." (PMID 41283645, 2025). "CXCL12 can be secreted by various cell types including fibroblasts, endothelial cells, macrophages, and tumor cells." (PMID 41376630, 2025). "CXCR4, a G-protein-coupled receptor, binds specifically to its ligand CXCL12, promoting tumour cell proliferation, metastasis, immune evasion, and stromal remodelling." (PMID 41002447, 2025). "CXCL12 expression in the tumor stroma was investigated in 70 tissue samples of canine epithelial malignant tumors." (PMID 40849508, 2025). "FAP+ CAFs, as the primary source of CXCL12 within tumors, secrete CXCL12 that enriches on the tumor cell surface." (PMID 40890855, 2025).
tumor (continued). "The CXCL12/CXCR4 paracrine signaling promoted stromal–epithelial interactions with resulting aggressive tumor behavior." (PMID 39714760, 2025). "For example, the CXCL12/CXCR4 axis promotes tumor proliferation, angiogenesis, and immune evasion by recruiting immunosuppressive cells such as regulatory T cells (Tregs) and myeloid‐derived suppressor cells (MDSCs)." (PMID 40145607, 2025). "Originally identified as a co‐receptor for HIV‐1 in CD4+ T cell infection, CXCR4 expression has been detected in numerous cancer cells, often overexpressed at tumour sites alongside elevated stromal tissue CXCL12 levels." (PMID 39779470, 2025). "CXCL12 plays a role in the mobilization and recruitment of these cells to the neoangiogenic niches supporting the revascularization of ischemic tissue and tumor growth." (PMID 40142155, 2025). "For instance, CXCL1 and CXCL12 enhances the tumor’s resistance to radiation through both direct and indirect mechanisms." (PMID 40134607, 2025). "Targeting the CXCL12/CXCR4 signaling pathway by inhibiting their binding or by blocking the expression of CXCL12 can reduce the accumulation of immunosuppressive cells and enhance the anti-tumor immunity." (PMID 41376630, 2025). "The group S6 is characterized by a CK+ER+CXCL12+ tumor niche pattern, featuring the co-localization of CKmedERlow and ERhighCXCL12+ tumor cells." (PMID 40182181, 2025). "Observational studies assessing tumor CXCL12 expression and survival outcomes in GC patients were included." (PMID 40481962, 2025). "In the tumor context, our results show the possibility that CAF-derived CXCL12 contributes to T cell accumulation in the tumor stroma." (PMID 40849508, 2025). "Conversely, a negative correlation was observed between Th1 cell infiltration and CXCL12 expression in most tumor types." (PMID 40166682, 2025). "In a mouse orthotopic xenograft, prostate cancer model treatment with selegiline decreased stromal expression of CXCL12 and restricted tumor growth." (PMID 39714760, 2025). "The rationale behind this combination strategy relates to the involvement of CXCR4 and its ligand CXCL12 in supporting tumor cell growth and angiogenesis, as well as immunosuppression in the tumor microenvironment." (PMID 40918456, 2025). "Specifically, CAF-derived TGF-β enhances the secretion of immunosuppressive factors and chemokines, such as C-X-C motif chemokine ligand 12 (CXCL12), that coat tumor cells and establish a milieu permissive for immune quiescence." (PMID 41425253, 2025). "Tumor cells can secrete CXCL12, which recruits these immunosuppressive cells into the TME by binding to C-X-C chemokine receptor type 4 (CXCR4) on the surface of immune cells." (PMID 41346580, 2025). "Conversely, iCAFs secrete inflammatory cytokines like IL-6 and CXCL12, driving tumor cell proliferation, angiogenesis, and immune escape." (PMID 40177538, 2025). "Nearby healthy cells, such as fibroblasts, can offer protection to tumours through remodelling of the extracellular matrix and production of chemo-repulsive cytokines such as CXCL12, and these behaviours can be induced by TGFβ expression by the tumour 68–70." (PMID 40768308, 2025). "Whereas, in our study, we compared the fold changes of the chemokines' mRNA relative expression in peritumor tissues vs tumor tissues and the CXCL12 was most highly expressed in peritumor tissues." (PMID 40756343, 2025). "CXCL12 facilitates tumor invasion and metastasis, while CCL11, CXCL14, CCL6, and CCL12 further contribute to chemoresistance and metastasis by enhancing glycolysis." (PMID 40230452, 2025). "Whereas CXCL12/CXCR4 signaling assists tumor cells in reaching LNs, FAK/RhoA signaling controls cell migration." (PMID 40584290, 2025). "Disrupting CXCL12 from CAFs enhances T cell-mediated tumor control, and targeting focal adhesion kinase (FAK) in cancer cells simultaneously reduces stromal fibroblast activation and the formation of an immunosuppressive milieu." (PMID 40313969, 2025).